FABP2 (fatty acid binding protein 2)
Diseases named in the same sentence as FABP2 in open-access papers (continued):
Sharing a sentence is not in itself a finding about the gene and the disease.
morbid obesity (1 paper, 2023). An excess of body weight, normally defined as an individual with a body mass index greater than 35 or a body weight greater than one hundred percent of ideal body weight. "It has been previously postulated that the I-FABP serum levels increase in people with morbid obesity and chronic hyperglycemia representing higher enterocyte loss through the role of FABP2 gene expression." (PMID 36701395, 2023).
small cell carcinoma (1 paper, 2017). A neuroendocrine carcinoma composed of small malignant cells which are often said to resemble "oat cells" under the microscope.
transient ischemic attack (1 paper, 2024). A brief attack (from a few minutes to an hour) of cerebral dysfunction of vascular origin, with no persistent neurological deficit. "FABP2 was downregulated in the plasma of AD cases, and certain polymorphisms of the gene were more frequently associated with transient ischemic attacks and non-cardioembolic infarction." (PMID 39766777, 2024).
variceal (1 paper, 2022). "The central role of bacterial and endotoxin translocation (due to a disrupted intestinal barrier) in variceal bleeding is further supported by our finding of increased FABP2 levels in variceal bleeders." (PMID 35308545, 2022).
infection (26 papers, 2016 to 2025). The state of being infected such as from the introduction of a foreign agent such as serum, vaccine, antigenic substance or organism. "Herein, the long-term administration of MSP upregulated SGLT-1, GLUT-2, CAT1, and FABP-2 genes associated with nutrient transportation even after L. monocytogenes experimental infection." (PMID 36009671, 2022). "Transcription of genes related to digestion (APN, MCT1, FABP2, and MUC2) were primarily influenced by infection at 7 d PI and tributyrin supplementation (FABP2 and MUC2) at 10 d PI." (PMID 33652244, 2021). "The FABP2 mRNA levels at 10 d PI were similarly affected by infection (P = 0.0012) with lower levels in the EM groups." (PMID 33652244, 2021). "Only one gene (FABP2) appeared to be significantly impacted by both primary infection and re-infection with E. coli O157:H7." (PMID 28003017, 2016). "In the present study, we found that the high expression level of FABP2 was positively corrected with the severity of diarrhea in E. coli F17 hosts, indicating that it may serve as a candidate biomarker for E. coli F17 infection." (PMID 35498757, 2022). "Alternatively, or additionally, plasma FABP2 levels may be reduced as the gene’s expression is downregulated in enterocytes due to infection or an aspect of hyperinflammation itself." (PMID 36335131, 2022). "In the present study, higher concentrations of thymol nanoemulsion greatly upregulated genes encoding occludin, zona occludens-1, claudins -1, JAM, MUC-2 and FABP2 controlling the barrier functions even after experimental infection, and it was better than thymol." (PMID 33833292, 2021). "The mRNA levels of FABP2 were significantly impacted by infection (P < 0.0001)." (PMID 33652244, 2021). "In addition, VBNC-BMDM infection up-regulated Fabp1 and Fabp2 and down-regulated Fabp4." (PMID 39714095, 2025). "The decrease in serum DAO and FABP2 levels further supports ghrelin’s barrier-strengthening effects, which could have significant implications for preventing the progression from local infection to systemic sepsis." (PMID 39857660, 2024). "In the extension of these studies, we found that by day 14 of Cr infection, 90% of LY6G+ DCC and FABP2+ PCC cells from the mid–distal colon upregulate MHCII, compared with 20% of FABP2+ PCCs and distal illeal enterocytes." (PMID 38600382, 2024). "Meanwhile, dietary EOA treatment also upregulated CLDN-1, OCLN, ZO-1, MUC2 and FABP2 mRNA levels at the middle infection phase, as well as linearly reduced the gene expression level of TLR4, NF-κB and IL-1β at the early infection stage in infected broiler chickens." (PMID 37391807, 2023).
cancer (8 papers, 2018 to 2025). A tumor composed of atypical neoplastic, often pleomorphic cells that invade other tissues. "Decreased TNF-α levels/Increased the relative abundance of Paracoides/Down-regulated three genes (Hmgcs2, Fabp2, and Gpt) associated with inflammation and cancer." (PMID 39712006, 2024). "Alternating the consumption of β‐glucan and quercetin significantly decreased the TNF‐α level, increased the relative abundance of Parabacteroides, and downregulated three genes (Hmgcs2, Fabp2, and Gpt) that are associated with inflammation and cancer." (PMID 31660141, 2019). "Moreover, the altered intestinal ecosystem due to alternating the consumption of β‐glucan and quercetin can further result in the downregulation of 3 cancer‐associated genes (Hmgcs2, Fabp2, and Gpt)." (PMID 31660141, 2019). "However, recent studies have found that abnormal expression of FABP2 is associated with the tumorigenesis and progression of various cancers and may affect the metabolic adaptability and proliferative capacity of tumor cells." (PMID 40717587, 2025). "To investigate the mechanisms orchestrating cancer stemness and tumour development, we analysed the transcriptional differences between differentiated (Krt20+Apoc2+Fabp2+) and stem (Lgr5+Cd44+Sox9+) cancer cells within tumours." (PMID 38658753, 2024). "The role of FABP2 in cancer may involve multiple mechanisms, including: lipid metabolism regulation: FABP2 affects the uptake and utilization of fatty acids by tumor cells, thereby influencing tumor energy metabolism." (PMID 40717587, 2025). "However, the role of FABP2 may be heterogeneous across different cancers, and future research should further explore the specific mechanisms of FABP2 and evaluate its potential in clinical applications." (PMID 40717587, 2025). "FABP4 overexpression is a tumor-promoting molecule in most cancer types, suggesting that NSC3852 may inhibit histone deacetylation and promote fatty acid transportation via FABP2 and/or FABP4." (PMID 39859448, 2025).
metabolic disease (8 papers, 2012 to 2024). A congenital disorder (due to inherited enzyme abnormality) or acquired (due to failure of a metabolically important organ) disorder resulting from an abnormal metabolic process. "Previous reports showed that the variants of FABP2 increased flux of dietary fatty acids into the circulation, and was also associated with increased fasting inculin concentration, fasting fatty acid oxidation and reduced glucose uptake, all are etiology of metabolic disorders." (PMID 22697793, 2012). "The role of FABP2 in metabolic diseases was also demonstrated in Fabp2-null mice that showed a significant reduction in FFA incorporation into triglycerides." (PMID 35887100, 2022).
tumor (8 papers, 2010 to 2025). "We also observed temporal changes in other key genes: lipid metabolism-associated genes such as APOA4, FABP1, and FABP2 were upregulated over time, which is consistent with reports that excess lipids promote tumor cell proliferation, colonization, and metastasis." (PMID 41009818, 2025). "Furthermore, Smad4 deficiency in macrophages promoted MC38 tumor growth in myeloid-specific Smad4 deficient (Lyz Smad4-/-) mice, whereas blocking Fabp2 expression reversed the tumor growth." (PMID 39664586, 2024). "Signaling pathway regulation: FABP2 may influence tumor cell differentiation and proliferation through signaling pathways such as Wnt/β-catenin/PPARγ and BMP4/Notch." (PMID 40717587, 2025). "For example, the use of FABP2 inhibitors may reduce the dependence of tumor cells on fatty acids, thereby inhibiting tumor growth." (PMID 40717587, 2025). "Inflammation and immune regulation: The expression of FABP2 in macrophages may affect M2 macrophage polarization, thereby influencing the tumor microenvironment." (PMID 40717587, 2025). "Subsequent studies have demonstrated that suppressing Fabp2 expression weakened macrophage M2 polarization and lipid metabolism following macrophage-specific Smad4 depletion, and effectively reversed the accelerated MC38 tumor growth caused by myeloid cell-specific Smad4 deletion." (PMID 39664586, 2024). "Furthermore, using Fabp inhibitor to block Fabp2 results in an anti-tumor effect." (PMID 39664586, 2024). "However, emerging evidence also supports the relevance of less characterized subtypes (e.g., FABP2, FABP8, FABP12) in tumor biology." (PMID 40717587, 2025). "Furthermore, western blot analysis of tumor tissues confirmed that myeloid cell-specific Smad4 ablation promoted STAT6 phosphorylation, whereas blocking Fabp2 reversed this phenomenon." (PMID 39664586, 2024). "However, mRNA expression levels of FABP1, FABP2, FABP5, FABP6, FABP7, FABP9, or FABP12 did not significantly differ in different tumor stages in CRC patients." (PMID 34680577, 2021). "Thus, changes in Gast, Ccla3, Glycam1, Spp1, Serpina1a, Cela1, Cldn2, and Fabp2 are a result of GW501516 treatment and are not tumor specific." (PMID 21318167, 2010).
cardiovascular disease (7 papers, 2011 to 2023). "Fabp2 and Fabp5 have been implicated in the pathogenesis of allergic airway inflammation as well as chronic inflammation associated with cardiovascular disease." (PMID 21738667, 2011). "The Ala54Thr polymorphism of FABP2 is associated with metabolic or cardiovascular diseases." (PMID 37091779, 2023). "Because the FABP2 Thr54 polymorphism appears to be prevalent in hypertriglyceridemic subjects, increasing EPA intake in these subjects could be an effective strategy for preventing cardiovascular diseases." (PMID 23497599, 2012).
psychiatric disease (4 papers, 2013 to 2025). "Although it is increasingly recognized that FA-metabolism may play an important role in psychiatric disease, this is – to the best of our knowledge – the first investigation of the role of FABP2 in a psychiatric population." (PMID 24340071, 2013).
bacterial diseases (2 papers, 2016 to 2021). "To examine if bacterial infections could be influencing the release of the inflammatory and anti-inflammatory cytokines, we measured levels of the LPS, FABP2, MIF and sCD14 molecules." (PMID 26814478, 2016).
immune disorders (2 papers, 2024 to 2025). "The high expression of differentially expressed genes, such as TLR4, CXC-8, PLA2/G7, HBEGF and FABP2, and the overactivation of immune pathways shown by GSEA prove that immune disorders are involved in the onset of NEC." (PMID 38814387, 2025).
retinopathy (2 papers, 2021 to 2023). "We showed in T1D diabetic individuals that gut permeability correlates with disease severity, as the highest levels of PGN, FABP-2 and LBP were seen in the most advanced retinopathy." (PMID 36902558, 2023).
FABP2 also shares sentences with these, for which no sentence is quoted: ischemia (25 papers); enteropathy (11); Anxiety (10); inflammatory bowel disease (10); endotoxemia (9); intestinal disease (9); Shock (6); Crohn disease (5); liver disease (5); atherosclerosis (4); co-infection (4); fibrosis (4); intestinal obstruction (4); virus infection (4); AIDS (3); bacteremia (3); End Stage Liver Disease (3); Hepatic steatosis (3); Hyperglycemia (3); injury (3); malnutrition (3); melanoma (3); myocardial infarction (3); pulmonary disease (3); systemic inflammatory response syndrome (3); acute abdomen (2); acute kidney injury (2); acute pancreatitis (2); Arthritis (2); asthma (2).
A further 112 diseases each share a sentence with FABP2 in 2 papers or fewer.